ATF4 (activating transcription factor 4)
Diseases named in the same sentence as ATF4 in open-access papers (continued):
Sharing a sentence is not in itself a finding about the gene and the disease.
diabetes (47 papers, 2005 to 2025). "Relieved hyperglycemia-induced alterations in cellular growth, apoptosis, and calcium influx by inhibiting PERK–eIF2α–ATF4–CHOP signaling axis in OP associated with diabetes." (PMID 40496774, 2025). "Conversely, a recent study in β-cell-specific Atf4-deficient animal models exhibited exacerbated diabetes, evidenced by hyperglycemia, as well as markers of dedifferentiation." (PMID 40806129, 2025). "Our results are similar to those of previous reports showing that the deficiency of the genes induced by ATF4, such as Eif4ebp1 and Atf5, exacerbated hyperglycemia in the mouse models of diabetes." (PMID 34547510, 2021). "CHOP is induced predominantly by the PERK/eIF2α/ATF4 signaling cascade associated with ER stress, as well as by the IRE1α/Xbp-1 signaling pathway and the ATF6α transcription factor in different pathological conditions, including diabetes." (PMID 34834808, 2021). "Therefore, the ATF4-mediated pathway is critical for the preservation of β-cell identity, and the failure of this process is associated with the development of diabetes." (PMID 34547510, 2021). "Furthermore, the β-cell–specific deletion of Atf4 exacerbated diabetes and promoted β-cell loss during ER stress in Akita mice." (PMID 34547510, 2021). "Specifically, aggravated Smad3 signalling dependent mitochondrial and ATF4‐CHOP apoptosis pathways may be the underlying mechanism that link diabetes with aggravated ICH." (PMID 31922310, 2020). "In contrast, the present work elucidates a distinct and diabetes-specific mechanism in which C-PC directly modulates the AGE–RAGE axis to attenuate PERK–eIF2α–ATF4–CHOP-mediated ER stress and subsequent mitochondrial apoptosis." (PMID 41303562, 2025). "Activating transcription factor 4 (ATF4) is a conserved transcription factor of recent interest in its wide variety of diseases such as neurodegeneration, diabetes, cancer, and skeletal muscle aging." (PMID 37749371, 2024). "Diabetes, in this context, downregulates ATF4 to reduce GPX4 expression and suppresses GSR to decrease GPX4 activity in the human heart." (PMID 38824159, 2024). "Under ER stress in diabetes, ATF4 upregulates SNAT2 mRNA in β cells to stimulate amino acid influx and protein synthesis." (PMID 38071217, 2023). "ATF4 expression was (p < 0.05) higher significantly in rats with diabetes in comparison with the normal control group." (PMID 37280499, 2023). "It is worth noting that ATF4 mRNA can be detected in all tissues and represents a vital and promising target for tumors, diabetes, and retinal and neurodegenerative disorders." (PMID 36939351, 2023). "ATF4 is expressed in the rabbit preimplantation embryo, and maternal diabetes mellitus led to increased transcription of ATF4 in the EB cells." (PMID 37511535, 2023). "In contrast to DRlyp/lyp HCD rats, DRlyp/lyp HCD+Lp299v rats exhibited the greatest diabetes-free survival, the highest Atf6 expression, the lowest sXbp1 and Atf4 islet gene expression, and elevated ERAD-related activity." (PMID 36261888, 2022). "The data support a prior study that identified an essential role for ATF4 in diabetes-induced inflammatory cytokine production by Müller glial." (PMID 36309088, 2022). "Meanwhile, the application of QDD resulted in the downregulation of PERK, eIF2α, and ATF4 and the upregulation of autophagy in diabetic kidneys." (PMID 36091599, 2022). "Together with the recent observations, our data also indicated the tissue-dependent transcriptional regulation of the expression of ATF4-target genes, which leads to the protection of β-cells from diabetes." (PMID 34547510, 2021). "It was exhibited that AOX substances can upregulate ATF4 expression by scavenging ROS in hyperglycemic conditions and strongly suppressing RIP1 and RIP3 proteins, preventing necroptosis in diabetes-associated periodontitis." (PMID 34572060, 2021).
diabetes (continued). "IPA analysis of MAM proteome predicts that XBP1 activation is suppressed, although the level of some individual target proteins is increased; in contrast, the function of PERK/ATF4 pathway is significantly enhanced (p = 6.33E-03) in diabetes." (PMID 28522876, 2017). "Skeletal muscle atrophy is a debilitating condition caused by diverse stresses, including aging, diabetes, starvation, or muscle denervation, which is often characterized by a reduction in AKT signaling and an increase in ATF4 and caspase 3 activity, and autophagy." (PMID 40301189, 2025). "Downregulation of ATF4 ameliorated retinal inflammation in a mouse model of diabetes." (PMID 38913045, 2024). "Diabetes-associated periodontitis patients showed necroptosis with high levels of RIP1, RIP3, and p-MLKL in addition to high levels of ROS and AGE production, and decreased expression of activating transcription factor 4 (ATF4)." (PMID 34572060, 2021). "Since the deletion of Chop significantly reduces symptoms in several mouse models of diabetes, the ATF4-CHOP pathway in β-cell could be involved in the pathology of diabetes." (PMID 34547510, 2021). "Also ER stress is related to the increased ATF4 expression as well as β-cell apoptosis and the subsequent development of diabetes." (PMID 22028770, 2011). "In addition, overexpression of Atf4 compromises postnatal β-cell function, suggesting that maintenance of a balanced state or the context-dependence of ATF4-mediated transcriptional regulation are likely important in preserving β-cell function and thereby protection against diabetes." (PMID 34547510, 2021). "Such ATF4 oscillations may be transient in healthy individuals but more sustained, or of different character, in those with metabolic disorders affecting the liver that develop insidiously such as diabetes." (PMID 22848420, 2012). "Rats with diabetes mellitus showed higher levels of GRP78, p-PERK, ATF4, and CHOP in the kidneys, as well as enhanced apoptosis." (PMID 40907786, 2025). "To understand the effects of celecoxib on ER stress during diabetes-induced muscle atrophy, we used western blotting to detect the levels of p-Perk, p-EIF-2α, ATF4 and Chop, which related to ER stress." (PMID 38313305, 2024). "Specifically, five genes—ATF4, ATP1A1, B2M, CYBA, and PRNP—emerged with the highest inference scores in the context of T2D and Diabetes Mellitus, suggesting that these genes play critical roles in the molecular mechanisms underlying these conditions." (PMID 39926598, 2024). "Numerous studies have shown the upregulation of UPR pathway-related proteins, such as PERK, activating transcription factor 6, p-EIf2, CHOP, activating transcription factor 4 (ATF4), and IRE1α, in the heart in diabetes models." (PMID 35941186, 2022). "IHC staining analysis showed that both oxidative stress markers (DHE and 3-NT) and ER stress markers (ATF4 and CHOP) were increased in STZ-induced diabetic kidneys." (PMID 28427241, 2017). "In the present study, the expression of GRP78, ATF4 and CHOP were up-regulated, and the phosphorylation of eIF2α and JNK were increased in the livers of mice with STZ/HFD-induced diabetes, which were reduced by long-term administration of BAIBA for 4 weeks." (PMID 26907958, 2016). "ER stress is known to induce autophagy in various pathological conditions, such as high fat diet-induced metabolic disorders, and diabetes, possibly via the IRE 1/JNK/p38 pathway and ATF4 dependent activation." (PMID 26807981, 2016). "Emerging evidence suggests that diabetes can activate all three UPR branches in retinal cells, among which the PERK/ATF4 pathway is the most extensively studied in the development of diabetic retinopathy." (PMID 25530974, 2014). "The role of ER stress and ATF4 in regulation of inflammatory factors is further confirmed in Müller cells, which are considered to be the major source of VEGF in diabetic retina." (PMID 25530974, 2014).
diabetes (continued). "In patients with CKD due to hypertension and diabetes, a correlation between the expression levels of PERK (protein kinase R-like ER kinase) and ATF4 (activating transcription factor 4), two mediators of the UPR cascade, and the degree of kidney fibrosis was found." (PMID 40643483, 2025). "In addition, compounds that can target the downstream factors of ATF4, such as ATOH8, can act as potential therapeutic agents for diabetes." (PMID 34547510, 2021). "This conclusion is supported by recently published findings showing that the progression of β-cell dysfunction in diabetes prone db/db mice does not correlate with an increase in the expression of either ATF4 or CHOP." (PMID 24145577, 2013). "The pattern of expression of proteins involved in UPR, namely the PERK (EIF2α, ATF4 and CHOP) and IRE1 (XBP-1) pathways, was different in CDs/y DD from all other groups, with consistently lower levels of expression at 4 weeks after initiation of DD and coinciding with the development of diabetes." (PMID 36674879, 2023). "While we demonstrate that increased cl-ATF6 α and sXBP-1 levels are critical for diabetes-induced senescence within plaques of diabetic mice and, in hyperglycaemia-exposed endothelial cells, the PERK/ATF4 arm was not studied." (PMID 35889743, 2022). "In addition, Pio treatment in the diabetes group increased GRP78 (3.72-fold) mRNA levels further compared to the T2DM + MC group (T2DM + Pio vs. T2DM + MC, p < 0.001, n = 5); however, no change was observed in ATF4 and CHOP mRNA levels." (PMID 40160239, 2025). "We observed that ATF6, CHOP, ERN1, HSPA5, and ATF4 mRNA levels were significantly increased in tissues from subjects with diabetes, and this was supported by an increased expression of ATF6 and CHOP protein expression when compared with tissue from subjects without diabetes." (PMID 33028031, 2020).
prostate carcinoma (39 papers, 2009 to 2025). A carcinoma that arises from epithelial cells of the prostate gland. "Growth factor-independent activation of mTORC1 also occurs upon loss of the PTEN tumor suppressor, and rapamycin was found to decrease ATF4 protein levels and ATF4-dependent expression of representative gene targets in established PTEN-deficient prostate cancer cells, LNCaP and PC3." (PMID 33646118, 2021). "Here we report that treatment of DU-145 prostate cancer cells with physiological concentrations of BA causes mild ER stress with ER expansion, the formation of cytoplasmic stress granules, and activation of the eIF2α/ATF4 integrated stress response (ISR)." (PMID 25425213, 2015). "Other reports have shown that ATF4 mRNA is upregulated in several cancer cells, including lung and prostate cancer cells, under cisplatin treatment, transactivating the antioxidant response and autophagy pathways to promote chemoresistance." (PMID 34709767, 2021). "Hepatitis B, HTLV-I infection, and prostate cancer are related to transcription factors (Atf4 and E2f2)." (PMID 34987399, 2021). "PERK and eIF2α phosphorylation is suppressed in proliferative prostate cancer cells stimulated by androgens, whereas ATF4 is essential for prostate cancer growth and survival." (PMID 32310340, 2020). "Immunohistochemistry staining was used to evaluate the expression of ATP2A3 and ER stress biomarkers (BIP and ATF4) in human prostate cancer and para-carcinoma tissues." (PMID 31023247, 2019). "The induction of TRB3 and ATF4 expression was also observed in PC3 cells (human prostate cancer), HeLa cells (human cervical cancer), and TIG1 cells (normal human diploid fibroblasts)." (PMID 31461933, 2019). "Slc3a2 has been found to be upregulated in human prostate cancer cells in an ATF4‐mediated way 26 and we also found induced gene expression of Slc3a2 in the hypothalamic cell line." (PMID 28174690, 2017). "STEAP4 may cause the generation of reactive oxygen species (ROS) through its oxidoreductase activity, leading to the expression of transcription factor ATF4, which promotes the growth and progression of prostate cancer, eventually leading to chemoresistance." (PMID 39668818, 2024). "ATF4 has been found to be critical for survival and growth of prostate cancer." (PMID 38601083, 2024). "The direct interaction between SLFN5 and ATF4 in prostate cancer results in mTOR activation." (PMID 36900220, 2023). "In prostate cancer-related experiments, although downregulation of LAT1 and LAT3 in tumor cells inhibits the growth of prostate cancer cells, it remains to be determined what other mechanisms of prostate cancer resistance can be triggered by targeting LAT1 (such as activation of ATF4)." (PMID 35008399, 2022). "Therefore, we examined the expression of ER stress-related proteins, such as p-eIF2α and ATF4 in IATL-treated prostate cancer cells." (PMID 30541589, 2018). "Our observation that BA induces mild activation of ATF4 in prostate cancer cells may provide insight for understanding how boron supplementation increases bone mass and strength." (PMID 25425213, 2015). "Importantly, ATF4 levels are significantly increased in androgen‐independent prostate cancer metastasis compared to primary cancer (2.25‐fold; p = 3.82E‐7) 23, suggesting that activation of ATF4 transcriptional targets is important in either metastasis or maintenance of the metastatic tumour." (PMID 25693838, 2015). "ATF4 and c-MYC promote tumor cell growth by synergistically regulating MTHFD2, and MTHFD2 is identified as a biomarker or therapeutic target for prostate cancer." (PMID 38336749, 2024). "In postmitotic neuronally differentiated PC12 cells, coexpression of TRB3 with ATF4 prevents ATF4-induced apoptosis and TRB3 can function as a pro-survival factor in glucose-starved PC-3 prostate cancer cells and bone marrow-derived mast cells." (PMID 24490110, 2013).
prostate carcinoma (continued). "Finally, treatment with 250 nmol/L NXP800, but not its inactive chemical control CCT365248 at this concentration, resulted in increased eIF2α phosphorylation and ATF4, ATF6, and IRE1 protein expression in VCaP, LNCaP95, and 22Rv1 prostate cancer cells." (PMID 39787247, 2025). "Considering these data, we next investigated whether the NXP800-mediated increase in eIF2α phosphorylation and ATF4, ATF6, and IRE1 protein expression was beneficial or detrimental to these prostate cancer models studied." (PMID 39787247, 2025). "Interestingly, relevant research shows that ATF4 regulates 4F2hc, LAT1, and ASCT1 gene, with low expression in healthy prostate tissue and early prostate cancer." (PMID 34075107, 2021). "Marine, a herbal medicine derived from Sophora flavescens, induces anti-prostate cancer effects by activating GRP78, CHOP, and ATF4, phosphorylating eIF2α, and inhibiting the EMT process via the decrease of E-cadherin and the increase of N-cadherin and vimentin." (PMID 34830138, 2021). "This tissue-specific CHOP expression might differentiate the role of PERK pathway in prostate cancer and colorectal cancer, because CHOP is largely known as a pro-apoptotic protein, while ATF4 is primarily pro-cancer development and progression." (PMID 30824833, 2019). "While CHOP, the downstream protein of ATF4 is expressed in prostate cancer cells even in the absence of ER stressors, CHOP is not expressed in the CRC cells that we tested." (PMID 30824833, 2019). "Consistent with these discoveries, we further confirmed that treatment of VCaP, LNCaP95 and 22Rv1 prostate cancer cells with NXP800, but not the inactive chemical control CCT365248, increased eIF2α phosphorylation and ATF4, ATF6, and IRE1 protein expression." (PMID 39787247, 2025).
Hepatic steatosis (38 papers, 2014 to 2026). Steatosis is a term used to denote lipid accumulation within hepatocytes. "Pre-clinical studies have shown that carbon monoxide upregulates sestrin-2 through the PERK-eIF2α-ATF4 signaling pathway and alleviates dietary methionine/choline deficiency induced hepatic steatosis." (PMID 35958574, 2022). "Our previous studies indicated that ATF4 is a key regulator of lipid metabolism and thermogenesis 10, and ATF4 deficiency protects mice from high-carbohydrate diet-induced liver steatosis." (PMID 24373582, 2014). "On the other hand, ER stress induces hepatic steatosis via increased expression of liver VLDL receptor through direct binding of Activating transcription factor-4 (ATF4) to the promoter region of the gene encoding the VLDL receptor (VLDL-R), ultimately leading to deposition of triglycerides." (PMID 33066023, 2020). "In this study, ATF4 was identified as a key factor in the expression of Inhbe in response to hepatic steatosis both in vivo and in vitro." (PMID 39948368, 2025). "We demonstrated that direct binding of ATF4 to the proximal region of the promoter was critical for Inhbe expression under hepatic steatosis conditions." (PMID 39948368, 2025). "By using epistasis analysis, we found that the eIF2α-ATF4 pathway serves as the primary effector for liver steatosis." (PMID 39139065, 2024). "Overexpression of ATF4 triggers liver steatosis in zebrafish, while silencing of ATF4 leads to a reduction of lipogenic genes, including PPAR-γ, SREBP-1, ACC and FAS, in the liver and adipose tissue of mice." (PMID 38216941, 2024). "The excessive expression of activating transcription factor 4 (atf4) in zebrafish utilizing the Tet-off transgenic line, Tg(–2.5actb1:Tetoff-Atf4-2A-mCherry)zf2124, leads to the occurrence of hyperlipidemia and hepatic steatosis." (PMID 37759472, 2023). "ATF4 depletion protects mice against liver steatosis and hypertriglyceridemia in response to high fructose feeding." (PMID 37660122, 2023). "Despite its documented ability to support hepatic steatosis, ATF4 ablation enhanced DEN-induced tumorigenesis and NASH to HCC progression in HFD-fed MUP-uPA mice." (PMID 36996941, 2023). "Various components of ER stress play roles in regulation of lipid metabolism, and the PERK-eIF2α-ATF4 pathway has been identified as a critical component required for regulating lipogenesis and hepatic steatosis." (PMID 35315506, 2022). "It was shown that ATF4 gene knockout mice were protected against diet-induced obesity, hyperlipidemia, and hepatic steatosis." (PMID 35958574, 2022). "Genetic ablation of ATF4 resulted in hepatic steatosis in response to chemical induction of ER stress." (PMID 33548031, 2021). "AMPK inhibition and triglyceride accumulation stimulated hepatic steatosis in mice with liver-specific ATF4 knockout." (PMID 34689832, 2021). "FGF21 KO mice also presented with an increased incidence of fatty liver disease and very-low-density lipoprotein receptor levels via the activation of the eIF2a-activating transcription factor 4 (ATF4) pathway." (PMID 33498410, 2021). "The FGF21-KO mice increased hepatic steatosis and low levels of lipoprotein receptor protein via the activation of the eIF2a-ATF4 pathway." (PMID 33498410, 2021). "Recent data has revealed that the activated PERK–eIF2α–ATF4 pathway during ER stress induces hepatic steatosis via increase VLDLR by enhancing intracellular TG accumulation with VLDL uptake." (PMID 31632274, 2019). "Since ATF4 overexpression can induce endotrophic and intravascular lipid accumulation, and hepatic steatosis in zebrafish, we then investigated the effect of ATF4 overexpression on the expression of lipogenic and UPR target genes." (PMID 29180630, 2017). "ATF4-knockout mice showed protection from hypertriglyceridemia, diet-induced obesity, and hepatic steatosis." (PMID 26840310, 2016).